IL34 (interleukin 34)
Diseases named in the same sentence as IL34 in open-access papers (continued):
Sharing a sentence is not in itself a finding about the gene and the disease.
cancer (continued). "In this article, we review the available evidence supporting the role of IL-34 in promoting cancer resistance to chemotherapy and immunotherapy." (PMID 36765929, 2023). "IL-34 is overexpressed by cancers developing in the alimentary tract, such as esophageal squamous, gastric cancer, and CRC, as well as by ovarian, lung, hepatocellular, and pancreatic cancers, and metastatic melanoma." (PMID 36765929, 2023). "The effect of M-CSF/IL-34-CSF-1R axis in malignancies is a good example since it covers both aspects." (PMID 37149693, 2023). "Cancer-derived IL-34 inhibits antitumor T cell-mediated immunity, impacting the effectiveness of PD-1 blocking treatment." (PMID 36798830, 2023). "In fact, IL-34 is abnormally expressed and promotes malignant proliferation in different types of cancers." (PMID 37149693, 2023). "The mechanism of MDSCs-mediated chemoresistance acquisition in cancer is not well known, but recent studies support the contribution of IL-34 in the modulation of MDSCs differentiation and function." (PMID 36765929, 2023). "Afterward, many authors have contributed to delineating the role of IL-34 in the control of the function of several cell types that sustain cancer initiation and progression." (PMID 36765929, 2023). "The combination of IL-34 inhibition with ICIs has raised its profile as a potentially essential treatment option for patients with cancer in the future." (PMID 36798830, 2023). "High IL-34 expression has been documented in various cancers where it plays important roles in multiple aspects of the tumorigenesis." (PMID 36359228, 2022). "IL34 production by chemo-resistant lung cancer cells has been reported to enhance the immunosuppressive profile of TAMs and contribute to cancer cell survival." (PMID 35664746, 2022). "Another known ligand is IL34, which role in cancer has been less explored partly due to its relatively recent identification as an alternative ligand." (PMID 35664746, 2022). "M-CSFR is expressed in many cancers and binds two competing ligands with high (M-CSF; Kd of 34 pM) and very high (interleukin-34 [IL-34]; Kd of 1pM) affinity." (PMID 35028604, 2021). "Recently, IL-34 has been identified as a ligand for CSF1R that is involved in promoting disease progression in various conditions ranging from inflammation to cancer." (PMID 33800170, 2021). "In the same study, the authors evaluated the impact of IL-34 expression in cancer tissues on patients’ survival." (PMID 34535634, 2021). "The expression levels of IL-34 in paired cancer and normal samples further confirm these results (P < 0.001)." (PMID 34336646, 2021). "Consistent with the data from TCGA, the expression of IL-34 in the cancer samples was lower than that in the normal samples (P < 0.001)." (PMID 34336646, 2021). "There is an increase in the serum levels of IL-34 under pathological conditions such as rheumatoid arthritis, systemic lupus erythematosus, Sjögren’s syndrome, systemic sclerosis, and cancer." (PMID 33800170, 2021). "Recent studies showed that IL34 is expressed in various types of cancers and is involved in cancer progression and metastasis." (PMID 34201353, 2021). "IL-34 has also been involved in the suppressive function of regulatory T cells, the activity of which associates with the progression of CRC cancer cells." (PMID 34535634, 2021). "Altogether, these data indicate that the role of IL-34 in cancers is extremely complex and likely context-dependent." (PMID 31968663, 2020). "In the autocrine pathway, IL-34 interacts with the M-CSF receptor on cancer cells to activate signaling pathways, stimulate the growth, and spread of cancer cells and increase their resistance to chemotherapy drugs." (PMID 33415105, 2020). "The results unveiled for the first time the responsible molecule Brd4 that regulates Il34 expression in cancer cells and suggested its possibility as a treatment target." (PMID 33072227, 2020).
cancer (continued). "It has been shown that IL-34 expression was upregulated in cancer cells upon stimulation with anticancer drugs that was implicated with cancer cells’ acquisition of resistance to chemotherapeutic treatment." (PMID 33072227, 2020). "Next, we showed that CD68/HLA-DRII-positive cells expressed IL-34 in both TICs and LPMCs preparations, even though the fraction of IL-34-positive cells was significantly higher in cancer samples." (PMID 33298879, 2020). "In conclusion, we identified here Brd4 as a responsible transcription regulator that controls Il34 expression in cancer cells." (PMID 33072227, 2020). "In the majority of cancers, increased synthesis of IL-34 results in enhanced tumorigenesis, whereas, in few and specific settings, IL-34 can negatively control cancer cell growth and diffusion." (PMID 31968663, 2020). "The demonstration that IL-34 stimulates IL-6 induction in both TICs and LPMCs supports further the protumorigenic role of IL-34, as IL-6 can target directly cancer cells and activate signaling pathways that promote CRC cell growth and survival." (PMID 33298879, 2020). "High expression of IL-34 has been documented in various cancers, where the cytokine is supposed to play important roles in multiple aspects of the tumorigenesis." (PMID 31968663, 2020). "Consistent with a pro-tumorigenic role of IL-34, many studies have documented the expression of the functional receptors of IL-34 in a variety of cancers." (PMID 31968663, 2020). "Our results fit with such observations and highlight the proliferative effect of IL-34 on cancer cells, as knockdown of IL-34 in CAFs attenuated the ability of culture supernatants of such cells to promote DLD-1 cell growth." (PMID 33260828, 2020). "According to the results, Il34 expression mechanism is suggested to be regulated by Brd4 in IL-34-producing cancer cells, which is efficiently suppressed with JQ1." (PMID 33072227, 2020). "In the autocrine pathway, IL-34 interacts with the M-CSF1-R on cancer cells, thereby activating signaling pathways that stimulate cancer cell growth and diffusion and/or enhance their resistance to chemotherapeutic drugs." (PMID 31968663, 2020). "Altogether, these observations raise the possibility that IL-34 can mediate the interplay between cancer cells and stromal cells during the colon carcinogenesis process." (PMID 33260828, 2020). "Co-culture of CRC cells with IL-34 AS-treated CAFs supernatants resulted in less cancer cell proliferation and migration." (PMID 33260828, 2020). "Conversely, we found that overexpression of IL‐34 promoted the carcinoma progression via EMT biomarkers (P < .01, P < .01, P < .01, respectively)." (PMID 32573824, 2020). "Our studies reveal the utility and complexity of single or combination therapeutics against CSF1 or IL34 as a bi-specific drug in inflammation or cancer." (PMID 31552020, 2019). "Immunohistochemical analysis of CRC tissue samples showed that both cancer cells and lamina propria mononuclear cells over-expressed IL-34." (PMID 29423057, 2018). "Analysis of cell sources of IL-34 showed that both cancer cells and mononuclear cells infiltrating the tumoral tissue produce elevated levels of the cytokine." (PMID 29423057, 2018). "Consist with these pro-tumorigenic functions, IL-34 expression was found to correlate with disease progression and poor prognosis in several cancers." (PMID 29515691, 2018). "Quantitative qRT-PCR showed detectable levels of IL-34 mRNA in different cancer cells with some variations." (PMID 29796177, 2018). "Data of the present study expand on these observations and indicate that IL-34 can directly target cancer cells and stimulate intracellular pathways that positively regulate colon carcinogenesis." (PMID 29423057, 2018). "Here, we set out to evaluate the effects of IL-34 and CSF-1 on cancer cell migration in transwell assays." (PMID 29796177, 2018).
cancer (continued). "Accordingly, we first analyzed the metabolic activity of MCs in co-culture with carcinoma cells as well as after treatment with IL-34." (PMID 26098772, 2015). "Yet treatment with IL-34 and co-culture with carcinoma cells partially rescued the anti-CSF-1 effects on MCs." (PMID 26098772, 2015). "Further, the expression of the alternative ligand IL-34 is organ specific and carcinoma cells produce significant amounts of CSF-1 as well as IL-34, which partially interferes with the anti-CSF-1 treatment effects." (PMID 26098772, 2015). "The role of IL34 in cancer progression is not fully understood, and whether it has a protective or detrimental effect depends on the tissue and cancer types." (PMID 41362277, 2026). "Further studies will obviously be needed to determine which members of the BMP family are IL34 partners in each organ, in normal physiology and pathological situations (for review 56) including cancers for which IL34 is already presented as a therapeutic target of major interest 57-59." (PMID 40083929, 2025). "In contrast to previous studies, our experiments excluded IL34-dependent effects on cancer cell proliferation, which could explain patient outcomes." (PMID 40538439, 2025). "Analysis of the differentially expressed genes (DEGs) in the MD-TAM cluster revealed that an IL34-enriched TME regulated the expression of various genes with either known or unknown roles in TAM or cancer progression." (PMID 40538439, 2025). "Coculture with either mouse or human RCC cell lines confirmed that IL34-OE cancer cells could enhance BMDMs migration." (PMID 40538439, 2025). "Bromodomain-containing 4 (BRD4), a transcriptional and epigenetic regulator, is over-expressed in IBD, and studies in cancer cells suggest that BRD4 might positively control IL-34 expression." (PMID 39451216, 2024). "Moreover, the knockdown of IL-34 in CAFs reduced the expression of these markers and their proliferative capacity and decreased the ability of these cells to induce the migration of cancer cells." (PMID 39457693, 2024). "Cancer cohort data were used to identify associations between SCC and IL34." (PMID 39619016, 2024). "Accumulating evidence indicates that IL-34 is produced in many cancers and supports the hypothesis that this cytokine triggers multiple signals that enhance cancer cell growth and diffusion." (PMID 36765929, 2023). "Furthermore, IL-34 and its functional receptors activate intracellular pathways that are involved in the development and progression of many different types of cancer." (PMID 36798830, 2023). "Therefore, IL-34 contributes to the development of ICI resistance in human cancer, and inhibiting IL-34 can restore the therapeutic effect of ICIs." (PMID 36798830, 2023). "It was also shown that expression of IL-34 was more pronounced in patients not responsive to neoadjuvant chemotherapy than in those who were responsive, and patients with cancers expressing high levels of IL-34 had worse prognoses as compared with patients with IL34-low carcinoma." (PMID 36765929, 2023). "However, further research is needed to fully understand the mechanisms underlying the role of IL-34 in TME and to determine the safety and efficacy of this approach in cancer patients." (PMID 36798830, 2023). "Preliminary evidence suggests that IL-34 signaling could make a contribution to cancer resistance to immunotherapy." (PMID 36765929, 2023). "In recent years, studies from several laboratories have shown that interleukin-34 (IL-34), a cytokine initially known to regulate the survival and function of monocytes/macrophages, is over-expressed in many cancers, where it regulates several cancer cell functions." (PMID 35837402, 2022). "However, observations about the role of IL-34 in other cancer types has so far shown contrary trends." (PMID 36438052, 2022). "Besides to regulate TAMs, accumulating evidence suggest that IL-34 stimulates cancer cell proliferation through its ability to interact with CSF1R in cancer cells." (PMID 36359228, 2022).
cancer (continued). "We next tested whether direct cell‐cell interactions between macrophages and cancer cells induced cancer cell activation by testing if direct co‐culture with macrophages influenced IL‐34 expression in cancer cells." (PMID 35132816, 2022). "Furthermore, in cancer, IL-34 has been described as a pro-tumorigenic factor in a variety of tumors." (PMID 33408768, 2021). "Recent studies have shown that IL-34 expression is upregulated in several cancers." (PMID 33800170, 2021). "An elevated expression of IL-34 was seen in other cancer types." (PMID 34535634, 2021). "The findings may help establish a new therapeutic strategy against IL-34-producing cancer in which usually an immunosuppressive environment is observed." (PMID 33072227, 2020). "Indeed, in cholangiocarcinoma, IL-34 produced by cancer stem cells (CSCs) stimulates macrophage infiltration, differentiation, and activation toward acquisition of CSC-associated macrophage phenotype." (PMID 31968663, 2020). "Moreover, it is becoming evident that interactions between IL-34 and its functional receptors trigger several intracellular pathways that ultimately control the growth and progression of many cancer types." (PMID 31968663, 2020). "In this article, we summarize the multiple roles of IL-34 in various cancers, with the aim to better clarify the relationship between the expression of this cytokine and cancer behavior and to provide new insights for exploring a new potential therapeutic target." (PMID 31968663, 2020). "In this brief report, we show for the first time that BET inhibitor JQ1 could reduce Il34 expression in two IL-34 highly producing cancer cells, such as OV3121-ras4 and HM-1." (PMID 33072227, 2020). "We found that the BET inhibitor JQ1 efficiently suppressed Il34 expression in cancer cell lines." (PMID 33072227, 2020). "In this review, we summarize the multiple roles of IL-34 in various cancers, with the aim to better understand the relationship between the expression of this cytokine and cancer behavior and to provide new insights for exploring a new potential therapeutic target." (PMID 31968663, 2020). "IL‐34 can be induced by cancer cells, which is believed to promote chemoresistance." (PMID 32573824, 2020). "We identified Brd4 as one of the critical molecules that regulate Il34 expression in cancer cells." (PMID 33072227, 2020). "IL-34 produced by cancer cells, has also been identified as a driver of chemoresistance." (PMID 29796177, 2018). "In this regard, the observed differences in the IL-34/CSF-1R ratio may play a role in both, myeloid and cancer cells." (PMID 29796177, 2018). "In addition, IL-34 has been shown to be involved in areas as diverse as neuronal protection, autoimmune diseases, infection, cancer, degenerative bone diseases and immune tolerance." (PMID 29796177, 2018). "Similarly, 77% of cancer tissues that showed strong staining of M-CSF were accompanied with high (56%) or weak (21%) expression of IL-34." (PMID 29323162, 2018). "In addition to its physiological functions, IL-34 is importantly involved in the pathogenesis of various diseases including autoimmune diseases, inflammation, infections, metabolic disorders, and cancer." (PMID 29515691, 2018). "Moreover, IL-34 facilitates polarization of memory T cells into Th17 cells, which enhance cancer cell growth in many organs." (PMID 29423057, 2018). "Interestingly, 91% of cancer tissues that showed strong staining of IL-34 were accompanied with high (48%) or weak (43%) expression of M-CSF." (PMID 29323162, 2018). "Immunohistochemistry analysis of CRC sections showed that IL-34 was mostly produced by cancer cells and to lesser extent by lamina propria mononuclear cells (LPMC) while staining of normal colonic sections revealed that IL-34 was weakly expressed by LPMC and virtually absent in epithelial cells." (PMID 29423057, 2018). "IL-34 plays a role in innate immunity, inflammation, and cancer." (PMID 29796177, 2018).
cancer (continued). "Furthermore, a meta-analysis of the prognostic value of the IL-34 gene in various types of cancer was performed." (PMID 25395235, 2015). "Therefore, we hypothesized that stromal components of the TME might drive IL34-dependent cancer progression." (PMID 40538439, 2025). "Therefore, the possibility to use inhibitors of IL-34 signaling to overcome cancer resistance could open up a promising opportunity for the treatment of such patients." (PMID 36765929, 2023). "Besides, this work may shed light on whether targeting IL-34 might be exploited as a potential treatment option for cancer patients in the future." (PMID 36798830, 2023). "CSF1R, the cellular receptor for Colony Stimulating Factor-1 (CSF1) and Interleukin 34 (IL-34), occupies a central role in manipulating the behavior of TAMs, and the dysregulation of CSF1R signaling has been implicated in cancer progression and immunosuppression in many specific cancers." (PMID 36983741, 2023). "Therefore, cancer therapy may gain a potentially game-changing new option if IL-34 inhibitors can be used to limit protumorigenic effects and ICI resistance." (PMID 36798830, 2023). "Cancer‐derived IL‐34 may play a role in resistance to immune checkpoint inhibition therapy." (PMID 35132816, 2022). "Support to this hypothesis comes from the demonstration that the in vitro generated, chemotherapy-resistant human lung cancer cell line, A549, and the corresponding in vivo chemo-resistant cancer cells produced IL-34 and induced a monocyte-derived immunosuppressive macrophage population." (PMID 35837402, 2022). "The factors and molecular mechanisms that regulate IL-34 in cancer cells remain unknown." (PMID 31968663, 2020). "Therefore, it seems important to understand the expression mechanism of IL-34 in cancer cells." (PMID 33072227, 2020). "We then tested whether JQ1 could really inhibit IL-34 expression in cancer cells." (PMID 33072227, 2020). "Based on these backgrounds, co-expression of both IL-34 and M-CSF - naturally or induced under therapeutic conditions - may characterize malignancies with enhanced aggression and has an impact on the clinical outcome of cancer therapy." (PMID 29323162, 2018). "For instance, IL-34 stimulates intestinal immune cells to make TNF-α and IL-6, two cytokines exerting proliferative effects on CRC cells, and has been involved in the suppressive function of regulatory T cells, a subset of T cells whose activity associates with the progression of cancer cells." (PMID 29423057, 2018). "Importantly, high co-expression of IL-34 and M-CSF associates with the poorest survival compared to cancers that show weak or absent expression of the two ligands." (PMID 29323162, 2018). "In particular, the interactions between interleukin‐34 (IL34) and its receptor, colony stimulating factor‐1 receptor (CSF1R), have emerged as key modulators of immune responses in various cancers." (PMID 41362277, 2026). "The potential interaction of IL34 with different members of the BMP family and their functional impact, including pathological situations such as cancer, should be further explored, opening new therapeutic perspectives." (PMID 40083929, 2025). "However, before moving into the clinic, further pre-clinical work is needed to better clarify if IL-34-mediated cancer resistance to therapies is either a general phenomenon occurring in all the patients who do not respond to such treatments or restricted to specific subsets of cancers/patients." (PMID 36765929, 2023). "The expression of intra-hepatic IL-34 is significantly upregulated in the livers of HCC patients, localized in the cytoplasm of hepatocytes, compared to that of non-cancer cohorts." (PMID 36438052, 2022). "IL‐34, M‐CSF and CCL2 were at first listed as factors related to macrophage chemotaxis, and their expression in HMDM and cancer cell lines were tested by real‐time PCR." (PMID 35132816, 2022).